CTSD (cathepsin D)
Diseases named in the same sentence as CTSD in open-access papers (continued):
Sharing a sentence is not in itself a finding about the gene and the disease.
tumor (continued). "A similar proportion of screened and unscreened tumours expressed c-erbB-2 oncoprotein and EGFR but expression of the oestrogen regulated protein cathepsin D was significantly more frequent in the screened group (P less than 0.05)." (PMID 1680369, 1991). "Furthermore, western blot also confirmed the aberrant expression of CTSL, CTSD, HSPA8, and XRCC4 in tumor tissues relative to paracancerous normal tissues." (PMID 41399382, 2026). "Our study also found that CTSD expression levels positively correlated with peripheral white blood cell counts and the proportion of bone marrow blasts, suggesting a potential link between CTSD and AML tumor burden." (PMID 41189142, 2025). "Further analysis revealed a positive correlation between PAI-1 expression and autophagy markers p62 (SQSTM1) and Cathepsin D (CTSD) in GBM tissues, suggesting that PAI-1 may be modulating GBM tumor biology through the process of autophagy." (PMID 40684232, 2025). "On the other hand, patients with Cathepsin D-negative tumours, who received tamoxifen therapy, did not have statistically different survival rates as patients who had not received the drug." (PMID 38578521, 2024). "In multivariate Cox-proportional hazards analysis, Cathepsin D expression was a significant prognosticator of BCSS (p = 0.021) independent of tumour grade, tumour size, lymph node stage and ER status." (PMID 38578521, 2024). "CTSD accelerates the migration and invasion of cells via ultrastructural modification and pseudopodia formation in SACC- LM cells, in addition to its proteolytic activity in the tumor microenvironment." (PMID 37198626, 2023). "The tumor cells maintained high levels of LAMP1 in the plasma membrane as was determined by FACS analysis of cells isolated from individual tumors, and Western blot shows higher levels of LAMP1 and CTSD in cells isolated from tumors formed by LAMP1Hi cells." (PMID 37003503, 2023). "Moreover, the treatment of tumor-bearing mice with LCL521, a lysosomotropic inhibitor of acid ceramidase, activates cathepsin B and cathepsin D, resulting in interrupted autophagy and ER stress." (PMID 35159308, 2022). "Furthermore, cathepsin activity assays conducted on tumor tissues revealed a dose-dependent decrease in CTSB and CTSD enzymatic activity." (PMID 36097006, 2022). "Using conditional CTSD knockout PyMT mice, we show that abrogating CTSD expression in mammary epithelial cells, but not in myeloid cells, delayed tumor development substantially." (PMID 33046706, 2020). "It has been reported to have autocrine properties and a number of mechanisms involving cathepsin D in the modulation of the extracellular matrix (ECM), thus facilitating the release of ECM-bound fibroblast growth factors and encouraging further tumor growth, angiogenesis, and cancer relapse." (PMID 32846884, 2020). "The role of pro-cathepsin D has not been completely elucidated; however, it has been suggested to be involved with tumour growth and invasion by intercellular communication." (PMID 32867726, 2020). "The possible involvement of cathepsin D and KLK3 in tumor metastasis could be addressed in the appropriate gene-targeted mouse models." (PMID 31099754, 2019). "In human CRC tissue, CTSD was detected in epithelial cells and in the stromal compartment at the more invasive areas of the tumor, but not in the normal mucosa, indicating that CTSD plays an essential role in CRC progression." (PMID 31497251, 2019). "MSCs are recruited to the tumor site from the bone marrow in response to soluble factors produced by tumor cells, such as IL-1, SDF-1, CCL5, and more recently the aspartic acid protease cathepsin D." (PMID 31547627, 2019). "From this cohort, 4 out of 5 of the proteins (IDH1, CTSD, PRDX6, and SERPINB6) also showed a statistically significant increase in abundance (12, 2.3, 2.6, and 3-fold, respectively) in the patient tumour samples when compared to the PDX F1 generation in the species-indistinguishable study." (PMID 30404163, 2018).
tumor (continued). "Besides CTSB, other CTSs, such as cathepsin D (CTSD), cathepsin L (CTSL) and cathepsin S (CTSS), showed highly expression in invasive tumor and increase motility of cancer cells." (PMID 27031837, 2016). "Interestingly, our data on exosomal protein profiles from treated Caco-2 showed an enrichment of upregulated proteins involved in tumor etiopathogenesis, including CRC (CD59, CRP, CTSD, HMMR, LY6K, TRIM22), and in cell cycle control (BRAF, CDC2, ERBB2)." (PMID 25594007, 2014). "Increased expression of MYB found in the tumor vs mets comparison (logFC 1.2) may also contribute to MMP1 down-regulation; Myb protein is known to up-regulate cathepsin D and MMP9 and down-regulate MMP1." (PMID 23405235, 2013). "They concluded that cathepsin D in the tumor cells at the IF area was not involved in tumor progression and metastasis in CRC." (PMID 22919486, 2012). "Neither cathepsin D expression in tumor tissue nor that in macrophages at the IF significantly correlated with any of the clinico-pathological parameters examined in our 119 patients." (PMID 22919486, 2012). "In CM from the three matched primary line pairs, cathepsin D was detected in only the tumour samples of two pairs and was absent completely in a third pair." (PMID 19789534, 2009). "Tissue cathepsin D did not correlate with tumour characteristics, unlike urinary cathepsin D in our study." (PMID 19789534, 2009). "pS2 and cathepsin D values obtained in ER-positive/PR-positive tumours did not significantly differ from the values obtained in ER-positive/PR-negative and in ER-negative/PR-positive tumours." (PMID 8123486, 1994). "Our data suggest that inhibition of CTSD and LOXL2 would not only have an anti-proliferative effect but may also be an effective therapeutic approach for eradicating residual disseminated tumor cells or maintaining them in a dormant state to avert cancer recurrence." (PMID 41185039, 2025). "Since CTSD cannot only be secreted by cells but is also efficiently taken up by cells through endocytosis, binding of extracellular CTSD by PEAR1 may also reduce intracellular levels of CTSD and thereby promote tumor cell quiescence." (PMID 41185039, 2025). "Studies of RNA levels of Cathepsin D showed that tamoxifen increased Cathepsin D RNA level regardless of the ER status of the tumours and that this increase is directly proportional to protein level in the cytosol in ER+ tumours but not in ER− tumours." (PMID 38578521, 2024). "In Cathepsin D-negative tumours, HER2 status did not affect BCSS." (PMID 38578521, 2024). "In addition to its proteolytic activity, cathepsin D promotes tumor growth through non-proteolytic mechanisms involving the activation of kinase pathways, namely, the ERK1/2 and AKT pathways." (PMID 37896224, 2023). "Indeed, previous studies showed that tumour pS2 concentration tends to be lower in postmenopausal patients, whereas cathepsin D tumour level does not show significant variation between pre- and postmenopausal patients." (PMID 33916398, 2021). "Expression of two lysosomal components CTSD (cathepsin D) and DRAM1 (damage-regulated autophagy modulator 1) was significantly up-regulated in both FL and DLBCL tissue biopsies, suggesting they may be expressed at higher levels in the tumor microenvironment." (PMID 25362242, 2014).
tumor (continued). "High CTSD mRNA levels correlated with shorter recurrence-free survival in TNBC, and extracellular cath-D was detected in the tumor microenvironment, but not in matched normal breast stroma." (PMID 30717773, 2019). "The aggressive breast cancer prognosis depends on demographic characteristics (age, menopausal status), tumoral (lymph node status, tumor size, pathologic type) and biological markers (presence or absence of HER2, the cathepsin D level)." (PMID 25870675, 2014). "Cathepsin D expression in the MTB did not correlate with age, gender, tumor location, histological type and grade, vascular invasion, perineural invasion, nodal status, or depth of invasion." (PMID 22919486, 2012). "In contrast, cathepsin D expression in stromal cells was an independent prognostic factor of longer DFS, but not OS, in IHC analysis of 80 OC, with no prognostic role observed for tumor cell expression." (PMID 24860785, 2014). "When cathepsin D expression was examined in TMAs from 119 patients with CRC, the higher expression at the IF relative to the MTB was confirmed, but this was largely related to its presence in macrophages rather than tumor cells per se." (PMID 22919486, 2012).
cancer (141 papers, 1993 to 2025). A tumor composed of atypical neoplastic, often pleomorphic cells that invade other tissues. "Several genes altered during activation are approved or potential drug targets, including HMGCR, FADS1/2 and CPT1A, while others, such as FASN, CD36, and CTSD, are directly implicated in cancer-related processes." (PMID 40759959, 2025). "Elevated levels of CTSD and LOXL2 were found in various tumors and patient plasma samples, and CTSD as well as LOXL2 have been consistently associated with unfavorable prognosis across various cancers." (PMID 41185039, 2025). "Of note, also end-stage MMTV-cre;Ctsd−/− tumors were CTSD-deficient in their cancer cell compartment." (PMID 33046706, 2020). "Several previous studies showed the level of pro-cathepsin D to be associated with progression of primary cancer." (PMID 32867726, 2020). "Cathepsin-D (CatD), owing to its dual role as a proteolytic enzyme and as a ligand, has been implicated in cancer progression." (PMID 32296755, 2020). "Apparently, cancers found a way to escape the growth arrest imposed by CTSD deficiency after a two-month latency period—just to grow and metastasize seemingly undisturbed." (PMID 33046706, 2020). "It should be noted that cathepsin D has also been implicated in cancer metastasis, where VEGF-C can also play a role." (PMID 31099754, 2019). "In contrast, an increase in extracellular CTSD expression and activity is associated with many types of cancers." (PMID 31060228, 2019). "Overexpression and secretion of the enzymes cathepsin D (CathD) and cathepsin L (CathL) is associated with metastasis in several human cancers." (PMID 30845739, 2019). "In this study, we have chosen to focus on the aspartic protease cathepsin D (CTSD) because of its reported association with cancer development." (PMID 31497251, 2019). "The Malmö Diet and Cancer Cardiovascular Cohort study revealed that high plasma level of cathepsin D was associated with increased risk of future coronary events during a mean follow-up time of 14.0 ± 4.3 years." (PMID 29375176, 2017). "For loss of Bcl-2, triple-negative BC were frequently associated with overexpression of cathepsin-D, and with aggressive disease course through lymph node invasion and high cancer cell proliferation/Ki-67 index." (PMID 27538498, 2016). "CTSB and CTSD degrade extracellular matrix proteins, and recently they have been implicated in cancer invasion and metastasis." (PMID 24717913, 2014). "Urinary cathepsin D was found to be significantly associated with overall (OS) (hazard ratio, HR, 1.33, 95%CI [1.09–1.63], P=0.005) and cancer-specific survival (HR 1.36, 95%CI [1.07–1.74], P=0.013) in RCC patients on univariate analysis." (PMID 19789534, 2009). "Furthermore, CTSD is highly expressed in breast, gastric, and ovarian cancers, where it is closely linked to cancer proliferation, angiogenesis, and metastasis." (PMID 40796615, 2025). "A study using a vectorized Cathepsin D inhibitor found that anti-proliferative activity was associated with Cathepsin D inhibition, suggesting that intracellular Cathepsin D plays a major role in cancer cell proliferation." (PMID 38578521, 2024). "Notably, cathepsin D is overexpressed in many cancers and has been associated with a poor prognosis." (PMID 37896224, 2023). "Cathepsin D is associated with poor prognosis in many cancer types including esophageal SCC." (PMID 34621666, 2021). "However, the cells responsible for this association and the function of CTSD in cancer are still incompletely understood." (PMID 33046706, 2020). "Furthermore, cathepsin D and ezrin are secreted aberrantly and excessively in various types of cancers, and are associated with increased cancer growth, invasion, and metastasis." (PMID 23389041, 2013).
cancer (continued). "Equipped with magnetic resonance contrast agents, pepstatin A-functionalized liposomes could be used as diagnostic tools in a wide array of cancers overexpressing cathepsin D. Moreover, liposomes could be loaded with a chemotherapeutic agent and thus utilized as a potent drug delivery system." (PMID 37896224, 2023). "Although cathepsin D has been implicated in acidic milieu of lysosomes with important consequences in regulation of apoptosis, it represents an important prognostic factor in a variety of cancers and is therefore considered to be a potential important molecule and influences cell signaling." (PMID 29375176, 2017). "Trajectory and pseudotime analysis showed that GTSE1+ OB cells were the origin of cancer cells, and CTSD+ OB cells were the end of cancer cells during the developmental trajectory." (PMID 40831537, 2025). "Cathepsin D (CTSD) has the ability to break down ECM and enables cancer extravasation which has been widely linked to cancer severity and adverse survival outcomes for patients." (PMID 41009609, 2025). "CTSD is an aspartic protease mainly involved in degrading unfolded proteins and that controls several processes in cancer progression, i.e., angiogenesis, invasion, metastasis, and drug resistance." (PMID 41227296, 2025). "Cancer cells can release an amount of pro-CTSD in the extracellular space which can act as an autocrine and paracrine factor to promote cell survival." (PMID 41227296, 2025). "CTSD has been reported to play a key role in regulating cancer invasion, migration, metastasis, and angiogenesis and serve as a promising target for the therapy of solid tumors." (PMID 40796615, 2025). "CTSD is mainly expressed in lysosomes, but CTSD and pro-CTSD are also released in the extracellular compartments from cancer cells to stimulate tumoral and stromal cells in the tumoral microenvironment." (PMID 41227296, 2025). "Recent findings have indicated that inhibition of CTSD enhances anticancer drug-induced apoptosis through the RNF183-mediated destabilization of BCL-XL in cancer cells." (PMID 40796615, 2025). "The suppression of the expression of GA-upregulated cancer proteins, including enolase-2, capping protein CapG, galectin-3, and cathepsin D, was observed after p70S6K1 downregulation/blockade." (PMID 40149589, 2025). "Increased TRIP-Br1 promotes mitophagy through upregulating CTSB and CTSD, which in turn inhibits cancer cell apoptosis and ultimately promotes cancer cell survival." (PMID 39013891, 2024). "Patients with cancers expressing Cathepsin D exhibited significantly lower BCSS if they had received tamoxifen (p = 0.001)." (PMID 38578521, 2024). "Prior studies have noted that Cathepsin D is involved in degradation of extracellular matrix and basement membrane in cancers due to its proteolytic activity." (PMID 38578521, 2024). "CTSD (Cathepsin D) is a key protein for lysosomal function that is necessary for autophagy in cancer cells." (PMID 39443755, 2024). "Specifically, cathepsin D has been the focus of many studies, elucidating its role in cancer and highlighting its potential as a biomarker or drug target, although research utilizing this potential remains limited." (PMID 37896224, 2023). "Inhibition of Cathepsin-D markedly enhances anticancer drug-induced apoptosis in a few human cancer cells." (PMID 37108361, 2023). "Conversely, the AhR complex inhibits ESR signaling in the presence of estrogen that would otherwise normally transcribe genes such as FOS, CTSD, HSP27, and TFF1, which are over-expressed and/or mutated in various cancers." (PMID 37027342, 2023). "On the other hand, DKK1, CTSB, CTSD, BCLX, CSF1, and CAPG are associated with the metastatic potential of cancer." (PMID 35745691, 2022). "Inhibition of cathepsin D (Cat D) sensitizes cancer cells to anticancer drugs via RNF183-mediated downregulation of Bcl-xL expression." (PMID 35715412, 2022).